BRAF (B-Raf proto-oncogene, serine/threonine kinase)
Diseases named in the same sentence as BRAF in open-access papers (continued):
Sharing a sentence is not in itself a finding about the gene and the disease.
colorectal cancer (continued). "Souglakos and associates demonstrated that BRAF mutations in primary colorectal cancer mark patients with poor prognosis regardless of specific treatment regimen." (PMID 24212832, 2011). "Tumours from 336 unselected colorectal cancer patients were analysed by three molecular tests (namely microsatellite instability (MSI), BRAF mutation and methylation of mismatch-repair genes), and patients were classified according to the RBG and AM II criteria." (PMID 20051945, 2010). "Colorectal cancer arises through a multistep carcinogenic process in which genetic and epigenetic alterations (e.g., microsatellite instability (MSI), CpG island methylation, mutations in KRAS, BRAF and PIK3CA) accumulate in a sequential manner." (PMID 20808308, 2010). "In addition, mutations in KRAS, BRAF and PIK3CA are associated with a worse outcome in patients with colorectal cancer." (PMID 20098682, 2010). "Analysis of dietary factors stratified by colorectal cancer gene mutation type showed that none of the dietary factors tested were positively or negatively associated with BRAF mutation." (PMID 20233436, 2010). "We first tested whether expression of BRAFV600E causes DNA hypermethylation by stably expressing BRAFV600E in the CIMP-negative, BRAF wild-type COLO 320DM colorectal cancer cell line." (PMID 20027224, 2009). "We first examined whether expression of BRAFV600E causes DNA hypermethylation by stably expressing BRAFV600E in the CIMP-negative, BRAF wild-type COLO 320DM colorectal cancer cell line." (PMID 20027224, 2009). "This study and our data suggest that BRAF may need to cooperate with other factors (genetic or epigenetic) to progress to colorectal carcinoma, as it was previously proposed for human naevi." (PMID 18782444, 2008). "By analogy with BRAF mutations, we wondered whether atypical KRAS mutations in colorectal cancers without BRAF mutations also tended to have concomitant mutations in Ras pathway genes." (PMID 39751654, 2025). "Moreover, vitamin C has been shown to selectively kill BRAF and KRAS-mutated colorectal cancer cells, further suggesting that low vitamin C levels may facilitate growth of BRAF-mutated tumors." (PMID 40102611, 2025). "None of the class 2 and 3 BRAF-mutant colorectal cancers had pathogenic POLE mutations." (PMID 39751654, 2025). "The FDA has approved the usage of a highly potent and specific MEK1/2 (MAPK pathway) inhibitor, Trametinib, in combination with BRAF inhibitor dabrafenib for all non-resectable or metastatic solid tumors (except colorectal cancer), as well as most pediatric gliomas harboring a BRAF V600E mutation." (PMID 40227649, 2025). "Recent evidence has demonstrated the advantages of using BRAF-targeted therapies, either alone or in combination with MEK inhibition and epidermal growth factor receptor-targeted treatment, in patients diagnosed with advanced colorectal cancer carrying the BRAF V600E mutation." (PMID 40731762, 2025). "However, there is a higher incidence of sporadic MSI in BRAF mutant colorectal cancer." (PMID 40362630, 2025). "In colorectal cancer, BRAF mutation is generally strongly associated with MSI-H, suggesting that MSI-H may be linked to a more favorable prognosis compared with microsatellite stability (MSS) within the BRAF mutation subgroup." (PMID 41458856, 2025). "However, clinical trial data reveal that BRAF mutations do not significantly influence the efficacy of immunotherapy in colorectal cancer patients." (PMID 39934467, 2025).
colorectal cancer (continued). "Some patients with colorectal cancer harbor a BRAF gene mutation and may not respond as well to treatment compared to patients without this mutation." (PMID 39766040, 2024). "It remains unclear whether intensification of the chemotherapy backbone in tandem with an anti-EGFR can confer superior clinical outcomes in a cohort of RAS/BRAF wild-type colorectal cancer (CRC) patients with initially unresectable colorectal liver metastases (CRLM)." (PMID 38728364, 2024). "Molecularly defined groups of colorectal cancers such as microsatellite instability (MSI)-high tumors and cancers with alterations in the receptor tyrosine kinase/KRAS/BRAF pathways, such as KRAS/NRAS or BRAF mutations and ERBB2 amplifications, may benefit from targeted therapies." (PMID 39452477, 2024). "Furthermore, the presence of mutations in BRAF has not yet been shown to have a prognostic value for use in the treatment of colorectal cancer." (PMID 39031216, 2024). "This case highlights that the BRAF non-V600 mutations, such as BRAF p.N581I mutant, may lead to resistance to epidermal growth factor receptor (EGFR) inhibitors and result in a rapid course in colorectal cancer." (PMID 37519790, 2023). "However, unlike the case of BRAF-mutated colorectal cancer, our combination of lapatinib and SHP099 integrated 2 different targets both upstream of KRAS and did not require MEK- or RAF-directed agents." (PMID 36752207, 2023). "One study exploring the treatment of BRAF-mutated CRC using a xenograft model, found that both pyrvinium and axitinib were able to significantly increase the ability of vemurafenib to attenuate tumor growth in xenografts of BRAF-mutated colorectal cancer cells." (PMID 37374338, 2023). "A high load of Fn has been associated with subtypes of colorectal cancers, located in the proximal colon, exhibiting microsatellite instability-high (MSI-H), MLH1 promoter hypermethylation, the CpG island hypermethylation phenotype-high, or BRAF mutation in some studies." (PMID 37772997, 2023). "In colorectal carcinoma, tumors with simultaneous presence of a high TMB and MSI/dMMR correspond to the CMS1 subtype, which is characterized by hypermutation, hypermethylation, enrichment in BRAF V600E mutations, as well as a strong infiltration of the tumor microenvironment with immune cells." (PMID 37190216, 2023). "BRAF gene abnormalities in small intestinal adenocarcinoma occur a little less than 10% of the time, but V600E mutations in small intestinal adenocarcinoma occur under 1% of cases, unlike in colorectal cancer." (PMID 35566730, 2022). "In conclusion, targeted therapies of colorectal cancers that possess BRAF mutations with or without PIK3CA mutations could be developed based on the global molecular environment of these cancers and based on vulnerabilities uncovered in in vitro models." (PMID 36295658, 2022). "Unveiling vulnerabilities of colorectal cancers with BRAF mutations with and without concomitant PIK3CA mutations may provide new opportunities for targeted treatments." (PMID 36295658, 2022). "However, the ‘German evidence-based guideline for colorectal cancer’ (2019) acknowledges the positive results of the TRIBE study, but highlights that the small number of BRAF mutated patients included only allows for establishing treatment hypotheses." (PMID 36819812, 2022).
colorectal cancer (continued). "In conclusion, the current study shows that the complex landscape of BRAF mutated colorectal cancer with or without concomitant PIK3CA mutations offers several leads for therapeutic targeting to improve outcomes of this subset of metastatic cancer patients associated with adverse survival." (PMID 36079062, 2022). "In a comprehensive analysis of advanced colorectal cancer and an evaluation of the concordance rate of a few driver mutations between primary and metastatic lesions, a concordance rate of approximately 95% was found when focusing on KRAS and BRAF hot point mutations." (PMID 35274488, 2022). "Compared with cell lines not bearing mutations in BRAF and PIK3CA, colorectal cancer cell lines with BRAF mutations with or without PIK3CA mutations show heterogeneous up-regulation in the mRNA expression of genes that are targets of the BRAF/MEK/ERK pathway." (PMID 36295658, 2022). "In 68 patients with colorectal carcinoma (CRC), key driver mutations were detected as follows: KRAS, 40 (59%); NRAS, 1 (1%); BRAF, 4 (6%); ERBB2, 2 (3%); and ERBB3, 1 (1%)." (PMID 35323313, 2022). "Secondly, in some patients, we could not collect information of BRAF mutational status (unknown: n = 46); these genes are well-known prognostic factors in colorectal cancer." (PMID 34715820, 2021). "In light of our new findings, it is likely that molecularly targeted therapies, such as KRAS inhibitors, BRAF inhibitors, angiogenesis inhibitors, and immune checkpoint inhibitors, should be validated for treating advanced-stage duodenal adenocarcinoma, similar to the studies of colorectal cancer." (PMID 34797780, 2021). "Similarly, BRAF V600E mutation and SRC mutations have been found to be mutually exclusive in colorectal cancer patients, and both could serve as molecular markers for prognosis." (PMID 34507532, 2021). "Consequently, dual targeting of cMet and BRAF in colorectal cancer may be a promising concept, and should be further explored, in particular since it may also offer hope to overcome resistance of several targeted drugs." (PMID 33014851, 2020). "Besides, KRAS mutation in colorectal cancer has been reported and KRAS/BRAF genes mutation might make EGFR inhibitors ineffective." (PMID 31998788, 2020). "Thus, there is a need for novel combination therapies with BRAF inhibitors in colorectal cancer." (PMID 32487991, 2020). "Furthermore, in colorectal cancer, high MGL ligand expression in tumors is associated with poor disease-free survival in late stage disease, whereby MGL ligand expression was highly correlated to mutations in the BRAF gene." (PMID 30761272, 2019). "BRAF mutations are present in both sporadic MSI-H and MSS colorectal cancers but mostly absent in Lynch syndrome, and so the presence of a BRAF mutation, in conjunction with MLH1 methylation analysis, reliably distinguishes between sporadic MSI-H colorectal cancer and Lynch syndrome." (PMID 31216061, 2019). "Glutathione was depleted by oxidative stress caused by increased DHA uptake via the GLUT1 glucose transporter and reduction of DHA back to vitamin C. Colorectal cancer cells with KRAS or BRAF mutation depend more on glycolysis than their nonmutated counterparts, not to mention normal cells." (PMID 31934267, 2019). "Additionally, BRAF p.V600E mutations are commonly found in tumours from non-sun-exposed tissues such as thyroid and colorectal cancers, demonstrating that this mutation can arise following mutagenic processes other than UV radiation exposure." (PMID 30412573, 2018).
colorectal cancer (continued). "The BRAF V600E mutation is increasingly being recognized as a negative prognostic factor particularly in late-stage colorectal cancer independent of associated clinicopathological variables and is one of the most consistent molecular markers that confer a poor outcome." (PMID 30598662, 2018). "However, whether the BRAF-mutant-specific miRNAs can contribute to oncogenesis of this more malignant subtype of colorectal cancer, remains unclear." (PMID 29115941, 2017). "In the case of colorectal cancer (CRC) the association of mucinous/serrated carcinomas with BRAF mutations is well known and we have shown that such association can be extended to the group of “BRAF-mutated-like” tumors, characterized by a specific genomic signature." (PMID 28523274, 2017). "Among non-MSI-high patients, BRAF mutation status was the most distinct marker that was strongly associated with other molecular events in the proximal colon cancer network, but not in the distal colorectal cancer network." (PMID 28623901, 2017). "In the 2012 Cancer Genome Atlas Network study, KRAS mutations presented in 43.0% of non-hypermutated colorectal cancers and 30.0% of hypermutated colorectal cancers while, BRAF mutations presented in 3.0% of non-hypermutated colorectal cancers and 47.0% of hypermutated colorectal cancers." (PMID 26910894, 2016). "Because there are many clinicopathological and molecular similarities between SSA/Ps and CIMP-high colorectal cancers, including proximal tumor location, BRAF mutation, and MLH1 methylation, SSA/Ps are hypothesized to be precursor lesions that develop into CIMP-high colorectal cancers." (PMID 26871294, 2016). "However, the preclinical and clinical performance of an NGS system for the detection of gene sets including minor mutations in KRAS, NRAS, and BRAF in patients with colorectal cancer has not been previously reported." (PMID 25954997, 2015). "BRAF p.V600E missense mutation is associated with poor prognosis in colorectal cancer and according to some recent reports, it has negative predictive value in anti-EGFR antibody therapy, though this has yet to reach sufficient levels of evidence to update clinical guidance." (PMID 25568935, 2015). "Here we report a patient with rectal cancer who carried the novel BRAF mutation VK600–601E, which has analogous molecular functions to those of the conventional BRAF mutation V600E, and may have potential as a prognostic marker for colorectal cancer (CRC)." (PMID 25636897, 2015). "Reports in colorectal cancer suggest BRAF-mutant tumors may escape inhibition by amplifying receptor tyrosine kinases, such as epidermal growth factor receptor (EGFR), and EGFR amplification and fusion are common alterations found in adult glioblastoma multiforme lesions." (PMID 24725538, 2014). "Using 23 colorectal carcinoma surgical samples collected with defined cold ischemic intervals and formalin fixation protocols, we studied the phosphorylation state of numerous PI3 Kinase pathway targets, as well as the BRAF V600E mutation and other markers using immunohistochemistry." (PMID 25409462, 2014). "Also it has a role in predicting colorectal cancers with worse prognosis and in identifying colorectal cancers lacking BRAF mutation that are more likely to respond to epidermal growth factor receptor inhibitor therapy." (PMID 24759670, 2013). "Similarly, BRAF mutation was not predictive for fluorouracil-based therapy in mostly stage II colorectal cancer." (PMID 24298448, 2013). "Combination therapy (e.g., BRAF and MEK inhibition concurrently) demonstrated superior efficacy to monotherapy (e.g. ORR 45-51% v 5-20% in colorectal cancer), with efficacy varying by histology." (PMID 42277540, 2026). "This review summarizes current evidence from pivotal phase II and III clinical trials, translational studies, and real-world data evaluating EGFR-, BRAF-, and HER2-directed therapies in colorectal cancer." (PMID 41899309, 2026).
colorectal cancer (continued). "Recent advancements in genome analyses, including the BRAF gene and mismatch repair (MMR) gene/microsatellite instability (MSI), have revealed the biological diversity of colorectal cancer (CRC)." (PMID 40548293, 2026). "Our findings reveal that 25.6% of TCGA colorectal cancer (CRC) tumors exhibit BRAF pathway activation, even in 19.4% of BRAF wild-type (WT) cases, suggesting alternative mechanisms driving pathway activation." (PMID 41648055, 2026). "qPCR analysis was performed to assess the expression levels of KRAS, BRAF, and PTEN genes in HCT116, HT29, and COLO205 colorectal cancer cell lines after NaB treatment." (PMID 40872562, 2025). "Analysis of larger colorectal cancer datasets further revealed consistent upregulation of EZH2, EED, and UHRF1 in BRAF-mutant CRCs compared to BRAF-wildtype tumors, reinforcing the broader relevance of these findings." (PMID 40678543, 2025). "Anti-EGFR therapies are used for other tumor types, including colorectal cancers (CRCs) with wt RAS and BRAF, which are treated with anti-EGFR monoclonal antibodies, such as cetuximab or panitumumab." (PMID 40846697, 2025). "Currently, the treatment regimens for most colorectal cancer (CRC) patients are mainly determined by several biomakers, including Microsatellite Instability (MSI), RAS, and BRAF." (PMID 40308511, 2025). "ARRY-162 (binimetinib) is a reversible MEK1/2 inhibitor which is often used in conjunction with encorafenib in BRAF V600E-mutant metastatic melanoma, NSCLC, and colorectal cancer." (PMID 40040723, 2025). "Equally important, this study demonstrates a significant link between the BRAF/MEK/PI3K oncogenic signature and the establishment of a pro-tumorigenic colorectal cancer microenvironment (TME)." (PMID 41009348, 2025). "LY3214996 proves effective in delaying or reversing resistance to BRAF and MEK inhibitors, and a synergistic effect was observed when combined with pan-RAF inhibitor LY3001920 in a KRAS-mutant colorectal cancer model." (PMID 38429288, 2024). "Cox regression analysis identified wild-type total RAS and BRAF, partial response (PR) + stable disease (SD), and high PNI values as influencing factors for OS in colorectal cancer patients." (PMID 39624124, 2024). "In this study, the GD2-CAR-T therapy was evaluated for the first time in metastatic melanoma patients in combination with BRAF/MEK inhibitor therapy, and as a monotherapy in patients with colorectal cancer and a patient with fibromyxoid sarcoma." (PMID 38754916, 2024). "PD-L1 inhibition by sparatlizumab improved effectivity of combined inhibition of BRAF and MEK with dabrafenib and trametinib in phase 2 clinical trial for colorectal cancer." (PMID 38774235, 2024). "We retrospectively analyzed the presence of BRAF and MMR aberrations and their correlation with the clinicopathological factors in 100 colorectal cancers of the 100 cases analyzed for BRAF and MMR." (PMID 39119381, 2024). "In colorectal cancer, ESMO suggests that an optimal gene panel should detect KRAS, NRAS, BRAF, NTRK, and ERBB2 amplification, although NGS is still only considered for research purposes." (PMID 38213074, 2024). "A study evaluated the efficacy of a combination therapy involving PD-1, BRAF, and MEK inhibitors in BRAFV600E mutant colorectal cancer." (PMID 39697234, 2024). "PDXEDEPMAP also detected markedly stronger KRAS essentiality in KRAS-mutant PDX of pancreatic ductal carcinoma (PDAC) and colorectal carcinoma (CRC) lineages, whereas BRAF essentiality was strongest in BRAF-mutant PDX of cutaneous melanoma (CM)." (PMID 39009815, 2024). "While BRAF inhibitor combinations with EGFR and/or MEK inhibitors have improved clinical efficacy in BRAFV600E colorectal cancer (CRC), response rates remain low and lack durability." (PMID 36702949, 2023). "There is another phase III clinical trial, NCT05217446, in progress to assess the efficacy and safety of BRAF inhibitors ± pembrolizumab in BRAF and MSI-H colorectal cancer patients." (PMID 38202120, 2023).